KRTAP10-2 (keratin associated protein 10-2)
Description:
In the hair cortex, hair keratin intermediate filaments are embedded in an interfilamentous matrix, consisting of hair keratin-associated proteins (KRTAP), which are essential for the formation of a rigid and resistant hair shaft through their extensive disulfide bond cross-linking with abundant cysteine residues of hair keratins. The matrix proteins include the high-sulfur and high-glycine-tyrosine keratins.
Synonyms: KAP10.2; KAP18-2; KRTAP10.2; KRTAP18-2; KRTAP18.2; KAP18.2
Tractability: No criterion of Open Targets' tractability assessment is met for any kind of drug.
Gene: Protein-coding gene on chromosome 21 (44,550,357 to 44,551,505, reverse strand). Ensembl gene ENSG00000205445.
Pathways (Reactome):
Developmental Biology: Keratinization
Gene Ontology:
Cellular component: cytosol; keratin filament
Genetic constraint (gnomAD): Loss-of-function variants: 1 observed, 1.01 expected, observed/expected ratio (o/e) 0.99, 90% interval 0.26 to 1.89. That is too few expected variants to judge how well the gene tolerates losing a copy. Missense variants: 293 observed, 313.18 expected, observed/expected ratio (o/e) 0.94, 90% interval 0.85 to 1.03. Synonymous variants: 133 observed, 127.79 expected, observed/expected ratio (o/e) 1.04, 90% interval 0.9 to 1.2.
Homologues: Orthologues: chimpanzee KRTAP10-2 (78% identical). Paralogues in human: KRTAP10-9 (88% identical), KRTAP10-11 (86% identical), KRTAP10-5 (81% identical), KRTAP10-4 (80% identical), KRTAP10-7 (78% identical), KRTAP10-6 (78% identical), KRTAP10-10 (71% identical), KRTAP10-1 (70% identical), KRTAP10-12 (66% identical), KRTAP10-3 (64% identical), KRTAP10-8 (60% identical), KRTAP16-1 (34% identical), and 35 more.